CCDC180 (coiled-coil domain containing 180)
Synonyms: C9orf174; DKFZp434I2420; BDAG1; FAP76; CFAP76; formerly KIAA1529
Gene: Protein-coding gene on chromosome 9 (97,307,304 to 97,378,751, forward strand). Ensembl gene ENSG00000197816.
Genetic constraint (gnomAD): Loss-of-function variants: 139 observed, 194.98 expected, observed/expected ratio (o/e) 0.71, 90% interval 0.62 to 0.82. The upper end of that interval is the gene's LOEUF score, 0.82, which puts it in group 3 of 6, group 1 being the genes least tolerant of losing a copy. Missense variants: 1,793 observed, 1,984.5 expected, observed/expected ratio (o/e) 0.9, 90% interval 0.87 to 0.94. Synonymous variants: 748 observed, 749.94 expected, observed/expected ratio (o/e) 1, 90% interval 0.94 to 1.06.
Homologues: Orthologues: chimpanzee CCDC180 (97% identical), macaque CCDC180 (93% identical), pig CCDC180 (70% identical), dog CCDC180 (68% identical), guinea pig CCDC180 (67% identical), mouse Ccdc180 (65% identical), rat Ccdc180 (64% identical), tropical clawed frog ccdc180 (33% identical). Paralogues in human: STRA6 (6% identical).
Diseases named in the same sentence as CCDC180 in open-access papers:
CCDC180 is named in the same sentence as 5 diseases in open-access papers, as found by Europe PMC text mining. Sharing a sentence is not in itself a finding about the gene and the disease. The quoted sentences say what the papers report.
migraine with aura (1 paper, 2025). A migraine disorder characterized by episodes that are preceded by focal neurological symptoms. "For migraine with aura, MICA (p = 2.82×10−7), GPATCH4 (p = 2.39×10−5), BBS4 (p = 7.64×10−4), ALMS1 (p = 8.40×10−4), and CCDC180 (p = 3.38×10−3) were the five most significant ones." (PMID 41261954, 2025).
renal cell carcinoma (1 paper, 2022). "When looking at the top 10 upregulated genes, we found for example Ccdc180, Col11a1, Gria2, or Prdm6 in males in relation to regulation of transcription, renal cell carcinoma, and fibrosis." (PMID 35230975, 2022).
cancer (1 paper, 2017). A tumor composed of atypical neoplastic, often pleomorphic cells that invade other tissues. "Those CNC variations associated with poor outcome (MUC5B, ZXDB, PLIN4, CCDC144NL, CNTNAP3B, and CCDC180) may probably facilitate cancer initiation and progression, and may be a new clue to study cancer metastasis and evolution." (PMID 29262625, 2017).
CCDC180 also shares sentences with these, for which no sentence is quoted: Behçet's disease (2 papers); tumor (1).